FLRT3 (fibronectin leucine rich transmembrane protein 3)
Description:
Functions in cell-cell adhesion, cell migration and axon guidance, exerting an attractive or repulsive role depending on its interaction partners. Plays a role in the spatial organization of brain neurons. Plays a role in vascular development in the retina (By similarity). Plays a role in cell-cell adhesion via its interaction with ADGRL3 and probably also other latrophilins that are expressed at the surface of adjacent cells. Interaction with the intracellular domain of ROBO1 mediates axon attraction towards cells expressing NTN1. Mediates axon growth cone collapse and plays a repulsive role in neuron guidance via its interaction with UNC5B, and possibly also other UNC-5 family members (By similarity). Promotes neurite outgrowth (in vitro). Mediates cell-cell contacts that promote an increase both in neurite number and in neurite length. Plays a role in the regulation of the density of glutamaergic synapses. Plays a role in fibroblast growth factor-mediated signaling cascades. Required for normal morphogenesis during embryonic development, but not for normal embryonic patterning. Required for normal ventral closure, headfold fusion and definitive endoderm migration during embryonic development. Required for the formation of a normal basement membrane and the maintenance of a normal anterior visceral endoderm during embryonic development (By similarity).
Synonyms: HH21
Tractability: Antibody: its Gene Ontology location is reachable by antibodies, with high confidence; UniProt places it where antibodies can reach, with medium confidence; UniProt predicts a signal peptide or a membrane-spanning region; the Human Protein Atlas places it where antibodies can reach. PROTAC: ubiquitination databases record sites on it; its protein half-life has been measured.
Gene: Protein-coding gene on chromosome 20 (14,322,985 to 14,337,631, reverse strand). Ensembl gene ENSG00000125848.
Subcellular location: Cell membrane; Presynaptic cell membrane; Endoplasmic reticulum membrane; Cell junction, focal adhesion; Secreted; Cell projection, axon; Cell projection, growth cone membrane
Subcellular location (Human Protein Atlas): Plasma membrane; Cell Junctions; Vesicles
Pathways (Reactome):
Developmental Biology: Signaling by ROBO receptors
Signal Transduction: Downstream signaling of activated FGFR1
Gene Ontology:
Molecular function: protein binding; protein homodimerization activity; protein-macromolecule adaptor activity; chemorepellent activity; fibroblast growth factor receptor binding
Biological process: cell-cell adhesion; neuron projection extension; embryonic morphogenesis; fibroblast growth factor receptor signaling pathway; head development; heart development; neuron projection development; proepicardium cell migration involved in pericardium morphogenesis; response to axon injury; synapse assembly; axon guidance; negative chemotaxis; synaptic membrane adhesion
Cellular component: plasma membrane; axon terminus; axonal growth cone; endoplasmic reticulum membrane; extracellular matrix; extracellular region; presynaptic membrane; synaptic membrane; axon; cell-cell junction; focal adhesion; glutamatergic synapse; growth cone membrane; postsynaptic membrane
Genetic constraint (gnomAD): Loss-of-function variants: 17 observed, 43.58 expected, observed/expected ratio (o/e) 0.39, 90% interval 0.27 to 0.58. The upper end of that interval is the gene's LOEUF score, 0.58, which puts it in group 2 of 6, group 1 being the genes least tolerant of losing a copy. Missense variants: 622 observed, 819.47 expected, observed/expected ratio (o/e) 0.76, 90% interval 0.71 to 0.81. Synonymous variants: 272 observed, 298.85 expected, observed/expected ratio (o/e) 0.91, 90% interval 0.82 to 1.01.
Homologues: Orthologues: chimpanzee FLRT3 (99% identical), macaque FLRT3 (99% identical), rabbit FLRT3 (99% identical), pig FLRT3 (98% identical), guinea pig FLRT3 (98% identical), dog FLRT3 (97% identical), mouse Flrt3 (96% identical), rat Flrt3 (96% identical), tropical clawed frog flrt3 (80% identical), zebrafish flrt3 (73% identical). Paralogues in human: FLRT1 (58% identical), FLRT2 (46% identical), LRRC15 (20% identical), LRRC4C (19% identical), LRRC4 (19% identical), LRRC4B (19% identical), LRRTM3 (18% identical), LRRTM4 (18% identical), PODN (17% identical), PODNL1 (17% identical), GP1BA (17% identical), RTN4RL1 (17% identical), and 10 more.
Diseases named in the same sentence as FLRT3 in open-access papers:
FLRT3 is named in the same sentence as 43 diseases in open-access papers, as found by Europe PMC text mining. Sharing a sentence is not in itself a finding about the gene and the disease. The quoted sentences say what the papers report.
colorectal cancer (6 papers, 2022 to 2024). A primary or metastatic malignant neoplasm that affects the colon or rectum. "Downregulation of FLRT3 expression promotes an aggressive phenotype in colorectal cancer cells, and downregulation of PDK4 is associated with poor prognosis in hepatocellular carcinoma." (PMID 38358909, 2024). "Flrt3 has been reported to suppress epithelial-mesenchymal transition (EMT) and promote apoptosis in colorectal cancer cells." (PMID 38254010, 2024). "Similarly, the role of TGF-β signaling in EMT was also demonstrated in colorectal cancer; CAFs promote EMT and invasion of colorectal cancer cells by activating the TGF-β/SMAD axis and attenuating the expression of FLRT3." (PMID 37461061, 2023).
breast carcinoma (5 papers, 2019 to 2024). "While some recent studies implicated FLRT3 in mediating tumor immune escape in acute myeloid leukemia and breast cancer, its role in directly modulating T cell activity in cancer has not been explored." (PMID 38427724, 2024). "MCF-7, BC-8701, and MDA-MB-231 breast cancer cells all expressed Tim-3, galectin-9, FLRT3, and at least one LPHN isoform." (PMID 31354733, 2019). "Besides, FLRT3 is overexpressed in breast cancer cells and participates in immune escape processes by regulating the immune receptor Tim-3 pathway." (PMID 36711387, 2022). "Based on these observations, it can be concluded that the FLRT3-LPHN-Tim-3-galectin-9 pathway is functional in other cancer cells and in particular in breast cancer cell lines and primary tumors." (PMID 31354733, 2019).
prostate carcinoma (5 papers, 2014 to 2025). A carcinoma that arises from epithelial cells of the prostate gland. "Treatment with α-LTX or FLRT3 was also found to induce the proliferation and migration of prostate cancer cells." (PMID 39000396, 2024). "In our study, we identified AOX1, APOC1, ARMCX1, FLRT3, GSTM2, and HPN as biomarkers associated with prostate cancer (PCa)." (PMID 37583929, 2023). "The possible prostate cancer (PCa) diagnostic biomarkers AOX1, APOC1, ARMCX1, FLRT3, GSTM2, and HPN were identified and validated using the GSE69223 and GSE71016 datasets." (PMID 37583929, 2023). "We next determined expression levels of MMP1 and FLRT3 in prostate tissue utilizing transcriptome sequencing data in prostate cancer." (PMID 25115393, 2014). "In addition, FLRT3- (a P4HA1-down-regulated gene) rescue experiments demonstrated its role in prostate cancer migration as assessed by the wound healing assay." (PMID 25115393, 2014). "In prostate cancer cells, we demonstrated that α-LTX and FLRT3 induced the expression of all three LPHNs and only LPHN3, respectively." (PMID 39000396, 2024). "We assessed the actions of LPHNs, including LPHN1, LPHN2, and LPHN3, in human prostate cancer lines via their ligand (e.g., α-LTX, FLRT3) treatment or shRNA infection, as well as in surgical specimens." (PMID 39000396, 2024).
lung carcinoma (3 papers, 2022 to 2023). "Additionally, we identified SFTPB (OR: 0.93, 95% CI 0.91–0.95), ICAM5 (OR: 0.95, 95% CI 0.93–0.97), and FLRT3 (OR: 1.10, 95% CI 1.05–1.15) as potential targets for lung cancer." (PMID 37735436, 2023).
colon cancer (2 papers, 2017 to 2024). "The effect of soluble FLRT3 Fc was tested in two HT-29 colon cancer models with either artificial/OKT3 or physiologic/allogeneic activation of T cells." (PMID 38427724, 2024). "Among them DGK1, HTR7, FLRT3, and ZBTB18 co-occurred with established regulators of human colon cancer pathobiology." (PMID 29344557, 2017).
melanoma (2 papers, 2007 to 2016). A malignant, usually aggressive tumor composed of atypical, neoplastic melanocytes. "Meanwhile, HLA-DRA, INHBA, DKK1, CTGF, PMP22, FLRT3 and NRCAM genes, upregulated in G10, were described as overexpressed in invasive melanomas." (PMID 27206673, 2016).
pancreatic cancer (2 papers, 2019 to 2021). "In renal clear cell carcinoma, higher expression level of FLRT3 was associated with a better survival of the patients during a 5-years follow-up time, while in one of the less vascularized cancers, pancreatic cancer, a lower expression level of FLRT3 associates with better prognosis." (PMID 30930791, 2019).
prostate tumor (2 papers, 2016 to 2023). "CRISP3 was upregulated; conversely, OGN, SPOCK3, COL4A6, CCBE1, and FLRT3 were downregulated in prostate tumor tissues." (PMID 37251946, 2023). "mRNA levels of FLRT3 and SLC14A1 also showed a stepwise reduction from benign to primary prostate tumor and metastatic samples in other clinical prostate datasets." (PMID 27732966, 2016).
Alagille syndrome (1 paper, 2020). "Duplication of JAG1, BTBD3, and FLRT3, or ASXL1 induces Alagille syndrome, neurological dysfunction or chromatin remodeling." (PMID 32684981, 2020).
asthma (1 paper, 2017). "Since FLRT3 represents the endogenous ligand for LPHN3, the effects observed in the present study may have physiological implications with respect to asthma in terms of increasing bronchial tone." (PMID 27325752, 2017).
breast tumor (1 paper, 2019). "Increased levels of LPHN2 and expressions of LPHN3 as well as FLRT3 were also detected in breast tumor cells." (PMID 31354733, 2019). "We found that primary breast tumors expressed galectin-9, Tim-3, LPHN2, and FLRT3; as well as detectable amounts of LPHN3." (PMID 31354733, 2019).
cardiac hypertrophy (1 paper, 2024). "Collectively, our findings illuminate the intricate roles of FLRT3 in cardiomyocyte apoptosis and autophagy, providing insights into prospective therapeutic strategies for cardiac hypertrophy and associated pathologies." (PMID 38509727, 2024). "In our results, FLRT3 expression was significantly decreased in H9C2 cells after silencing, suggesting its potential role in regulating cellular processes during cardiac hypertrophy." (PMID 38509727, 2024).
coronary artery disease (1 paper, 2019). "FLRT3 locates on chromosome 20 and is transcribed from the negative -strand in a region overlapping with MACROD2, a gene which polymorphism has been associated with the risk of coronary artery disease and hypertension." (PMID 30930791, 2019).
Kallman Syndrom (1 paper, 2019). "Links between FLRTs and diseases are virtually lacking as yet; there is one genome-wide association study for Kallman Syndrom (with anosmia as its most distinguishing feature) identifying three patients with mutations in FLRT3, all located in the LRR domain." (PMID 31297045, 2019).
Lissencephaly (1 paper, 2019). A spectrum of malformations of cortical development caused by insufficient neuronal migration that subsumes the terms agyria, pachygyria and subcortical band heterotopia. "Notably, the only two other genes known to maintain lissencephaly in the mouse (or any other lissencephalic species) are Flrt1 and Flrt3 which redundantly regulate neuronal adhesion during migration." (PMID 31729356, 2019).
metastatic prostate carcinoma (1 paper, 2014). A carcinoma that arises from the prostate gland and has spread to other anatomic sites. "We validated the FLRT3 results across benign, prostrate carcinoma and metastatic prostate cancer tissues by immunoblot analysis which confirmed the inverse correlation between P4HA1 and FLRT3." (PMID 25115393, 2014).
Obesity (1 paper, 2021). Accumulation of substantial excess body fat. "As we found in the survival analyses, 5 DE mRNAs (SORCS1, FLRT3, HIBADH, CATSPER1, and MAP3K8) and 5 DE miRNAs (hsa-miR-3130-2, hsa-miR-148b, hsa-miR-2681, hsa-miR-4487, and hsa-miR-3613) of obesity-related ccRCC were found in VAT." (PMID 34621242, 2021).
ovarian carcinoma (1 paper, 2024). A malignant neoplasm originating from the surface ovarian epithelium. "NP591 was further tested in a SKOV3-FLRT3+ ovarian cancer CDX model with endogenous FLRT3 expression in the presence of adoptively transferred human PBMCs." (PMID 38427724, 2024). "The therapeutic potential of FLRT3 blockade to enhance T cell–based immunotherapies in solid tumors was tested in zebrafish xenograft models of ovarian cancer (OVCAR-5) and RD together with EpCAM CAR-T cells or EGFR/CD3 BiTEs, respectively." (PMID 38427724, 2024).
papillary renal cell carcinoma (1 paper, 2024). A rare subtype of renal cell carcinoma, arising from the renal tubular epithelium and showing a papillary growth pattern, which typically manifests with hematuria, flank pain, palpable abdominal mass or nonspecific symptoms, such as fatigue, weight loss or fever. "Immunohistochemical (IHC) analysis of cancer FFPE tissues using an FLRT3 monoclonal antibody (mAb) showed the highest membrane FLRT3 expression on papillary renal cell cancer (RCC) and clear cell RCC, with less expression on other tumor types." (PMID 38427724, 2024).
peripheral nerve injury (1 paper, 2023). Injury to a peripheral nerve. "FLRT3 has previously been seen to be upregulated in the DRG following peripheral nerve injury and modulates neuron growth." (PMID 37298117, 2023).
renal carcinoma (1 paper, 2024). A carcinoma arising from the epithelium of the renal parenchyma or the renal pelvis. "Expression of FLRT3 on the cell surface of renal cancer suggests that blockade of the FLRT3-UNC5B pathway has the potential to benefit patients that are not effectively treated with existing immunotherapies." (PMID 38427724, 2024).
tumor (10 papers, 2014 to 2025). "FLRT3 Fc inhibited T cell–mediated reduction tumor growth, which was concomitant with attenuation of GVHD in both HT29-OKT3 and WT models." (PMID 38427724, 2024). "For example, FLRT3 is reported to be involved in the prevention of anti-tumor immunity via Tim-3-Galectin-9 pathway." (PMID 38225404, 2024). "Since there were few cases of distant metastasis in TCGA and CPGEA, other GEO datasets GSE6919 and GSE3325 were employed to examine the relationship between FLRT3 and tumor metastasis." (PMID 38225404, 2024). "FLRT3 expressed in human cancers favored tumor growth and inhibited CAR-T and BiTE + T cell killing and infiltration in humanized cancer models." (PMID 38427724, 2024). "To model FLRT3-expressing cancer in a cell line–derived xenograft (CDX) tumor model, we intradermally implanted 293T cells that ectopically expressed FLRT3 in NOD.Cg-Prkdc scid Il2rg tm1Wjl/SzJ (NSG) mice with adoptively transferred human PBMCs." (PMID 38427724, 2024). "FLRT3 blockade with NP591 significantly reduced tumor growth." (PMID 38427724, 2024). "FLRT3 overexpression enhanced 293T tumor growth in this model." (PMID 38427724, 2024). "The absence of FLRT3 causes changes in cell polarity, decreased adhesion, and enhanced cell motility, thus playing a role in tumor metastasis and invasion." (PMID 37251946, 2023). "Pathway analysis suggested that chemotaxis and integrin- and cadherin-mediated cell adhesion were the most functionally relevant processes (GeneGo Metacore), with two genes present in every sample type comparison (e.g. benign vs. tumor) across all studies - FLRT3 and SLC14A1." (PMID 27732966, 2016). "Among them, FLRT3, ATP1A1, and KCNJ15 were expressed at decreased levels in tumor samples, and the expression of SAA1 was increased in tumor samples." (PMID 38358909, 2024). "Using data from the HPA database, we found immunohistochemical images of five prognostic signature genes in normal and tumor tissues, including three upregulated genes (ANKLE1, PPP1R27, and AMH) and two downregulated genes (FLRT3 and PPBP)." (PMID 35676660, 2022). "Tumor tissue cells expressed LPHN2 (significantly higher levels compared to healthy tissues), LPHN3, and FLRT3 (LPHN ligand)." (PMID 31354733, 2019). "We identified multiple genes that were induced or repressed upon P4HA1 knockdown including those involved in tumor growth and invasion such as MMP1, MMP2 and FLRT3, among others." (PMID 25115393, 2014). "To explore the role of FLRT3 in PCa, we then compared the RNA level of FLRT3 between normal and tumor samples in CPGEA and TCGA." (PMID 38225404, 2024). "In the EpCAM/OVCAR-5 model, FLRT3 expression on tumors significantly reduced T cell–mediated antitumor immunity, inhibited T cell TME recruitment/infiltration, and reduced T cell engagement (close interaction) with tumor cells." (PMID 38427724, 2024). "Therefore, our study found that during PCa pathogenesis, the disorganized expression of CRISP3, OGN, SPOCK3, COL4A6, CCBE1, and FLRT3 leads to ECM dysfunction and promotes angiogenesis and tumor development." (PMID 37251946, 2023). "FLRT3 is most strongly co-expressed with tumor suppressor gene TP63 and angiogenesis regulator gene NTN4 (Pearson correlation r = 0.83) (CBioportal), which suggests possible mechanisms by which HNF1B could exert the effects observed here – a control switch preventing EMT in non-tumor tissue." (PMID 27732966, 2016).
cancer (8 papers, 2014 to 2024). A tumor composed of atypical neoplastic, often pleomorphic cells that invade other tissues. "To interrogate the relevance of FLRT3 in human cancers, we determined protein cell surface membrane expression on cancer cell lines and cancer patient formalin-fixed, paraffin-embedded (FFPE) tissues." (PMID 38427724, 2024). "Off note, expression of FLRT3 has prognostic value in certain cancers." (PMID 30930791, 2019). "Among them, we again identified three cancer-related genes (NEK7, UBE2D1 and FLRT3), whose mRNA expressions were repressed by miR-101 overexpression in SPAC-1-L cells and induced by AS-101 in HOUA-I cells." (PMID 25153722, 2014).
bacterial infection (1 paper, 2011). "Furthermore we have recently demonstrated that Flrt3 is induced by bacterial infection." (PMID 21490959, 2011).
FLRT3 also shares sentences with these, for which no sentence is quoted: infection (2 papers); acute myeloid leukemia (1); Alzheimer disease (1); amyotrophic lateral sclerosis (1); autism spectrum disorder (1); cerebral infarction (1); congenital hypogonadotropic hypogonadism (1); epilepsy (1); graft versus host disease (1); hepatocellular carcinoma (1); Hypertension (1); multiple sclerosis (1); neurodevelopmental disorder (1); Noonan syndrome (1); Parkinson disease (1); renal clear cell carcinoma (1); renal diseases (1); skin tumors (1); Supraventricular tachycardia (1).